CYP2J2 (cytochrome P450 family 2 subfamily J member 2)
Diseases named in the same sentence as CYP2J2 in open-access papers (continued):
Sharing a sentence is not in itself a finding about the gene and the disease.
breast carcinoma (9 papers, 2012 to 2025). "In a recent cohort study investigating the association of pharmacogenetic variations to hematologic toxicity in Ethiopian breast cancer patients, we reported that patients carrying CYP2J2*7 variant alleles were associated with higher incidence of hematological toxicity." (PMID 32390827, 2020). "In breast cancer, elevated expression of CYP2J2 was found associated with enhanced angiogenesis and tumor metastasis through EETs; However, the underlying mechanism of CYP2J2/EpOMEs in TNBC remains largely unknown." (PMID 39695149, 2024). "Breast cancer models predominantly expressed CYP2J2 and CYP2S1, whereas CYP3A and CYP2C subfamily members were enriched in hepatic cancer, underscoring their roles in xenobiotic metabolism and drug clearance." (PMID 41174467, 2025). "Our finding was consistent with the previous findings that CYP2J2 is significantly highly expressed in breast cancer at mRNA levels, with the highest expression in TNBC." (PMID 39695149, 2024). "We observed a 2- to 10-fold increase in the gene expression of CYP2C19 and CYP2J2 in the triple negative mammary tumor tissues compared with the paired normal tissues." (PMID 31072371, 2019). "CYP2J2-derived EETs have been shown to promote invasion and metastasis in a variety of human cancers, including breast carcinoma." (PMID 29050342, 2017). "Notably, the protein levels of CYP2J2 in tumor tissue from patients with TNBC were higher than other breast cancer subtypes." (PMID 39695149, 2024). "CYP2J2 is exclusively an epoxygenase expressed mostly in the heart, intestines, kidneys, and other tissues with increased, robust expression in multiple cancer cell lines and tissues including breast cancer." (PMID 32581794, 2020). "Breast cancer models, particularly MCF-7 cells, exhibited a different CYP450 profile, with CYP2J2, CYP2S1, CYP2A6 and CYP2A13 being the most prominent isoforms." (PMID 41174467, 2025). "In MCF-7 breast cancer cells, multiple CYP450 isoforms were identified, including CYP2A6, CYP2A13, and CYP2J2, albeit at lower sequence coverages ranging from 1% to 7%." (PMID 41174467, 2025). "Cyclophosphamide, the cornerstone of breast cancer chemotherapy in Ethiopia, is mainly metabolized to 4-hydroxy-cyclophosphamide by genetically polymorphic CYP3A, CYP2B6, CYP2C9, CYP2C19, and CYP2J2 enzymes." (PMID 31139078, 2019). "Numerous studies have examined the expression of several CYP isoforms in breast cancer, including aromatase/CYP19A1, CYP1A1, CYP1B1, CYP2J2, CYP2C, CYP3A, and the CYP4 family." (PMID 32581794, 2020). "To obtain a more clinically relevant measure of protein expression levels, we randomly selected clinical paraffin-embedded tumor samples representative of all the breast cancer subtypes and subjected them to IHC analysis against CYP2C19/9, CYP2J2, CYP3A4 and sEH antibodies." (PMID 31072371, 2019). "We found that expressions of certain CYP genes is correlated with node status (N stage) of breast cancer including CYP2A6 (p-value = 0.025), CYP2C8 (p-value = 0.035), CYP2D6 (p-value = 0.027), CYP2J2 (p-value = 0.036), CYP3A7 (p-value = 0.026), and CYP4B1 (p-value = 0.046)." (PMID 28684774, 2017). "Similarly, CYP2J2 and CYP2S1 expression in breast cancer models could influence drug metabolism and treatment response." (PMID 41174467, 2025). "Furthermore, we found that CYP2J2 had inverse expression levels to let-7b in four paired human breast cancer and adjacent nontumor tissues." (PMID 22761738, 2012). "Expression of CYP2C8/9 and CYP2J2, and/or high level of 14,15-EET detected in patients were found to be positively correlated with aggressiveness of human BC, or that might be involved in breast cancer cell epithelial-mesenchymal transition and cisplatin resistance." (PMID 31072371, 2019).
coronary artery disease (9 papers, 2008 to 2023). "The association of the CYP2J2 G-50T polymorphism with coronary artery disease has been explored, but the results remain controversial." (PMID 28938665, 2017). "In conclusion, our meta-analysis suggested that the CYP2J2 G-50T polymorphism was associated with coronary artery disease risk in the allele, homozygote and recessive models in Caucasians." (PMID 28938665, 2017). "Variants of CYP2J2 with lower activity are known in some populations to be linked to an increased risk of coronary artery disease." (PMID 19823578, 2009). "A large number of evidences demonstrated that polymorphisms in the CYP2J2 gene affect the risk and incidence of coronary heart disease in specific populations, and the plasma level of EETs is significantly elevated in patients with coronary artery disease without any change in DHETs levels." (PMID 35744996, 2022). "Polymorphisms in Cyp2J2 are associated with increased risk of coronary artery disease." (PMID 23967089, 2013). "Single nucleotide polymorphisms resulting in impaired transcription factor binding and thus the expression of the CYP2J2 gene, are present at a higher frequency in individuals with angiographically documented coronary artery disease." (PMID 35665247, 2022). "In explanted left ventricular tissue from humans with ischemic heart disease, CYP2J2 and CYP2C8 levels were lower in the infarcted regions." (PMID 35665247, 2022).
ischemia (9 papers, 2013 to 2025). A hypoperfusion of the BLOOD through an organ or tissue caused by a PATHOLOGIC CONSTRICTION or obstruction of its BLOOD VESSELS, or an absence of BLOOD CIRCULATION. "Transgenic mice overexpressing CYP2J2 have been shown to have less extensive infarctions and more complete recovery after ischemia." (PMID 38966316, 2024). "The group found that young mice (2–3 months) carrying the human CYP2J2 transgene had overall improved heart function post-ischemia when compared with wild-type mice." (PMID 29966295, 2018). "Overall, CYP2J2 overexpression in the heart has been shown to improve the outcomes of ischemia and/or ischemia-reperfusion injuries." (PMID 29966295, 2018). "Another study reported that the expression of CYP2J2 in cardiomyocytes led to improved functional recovery and reduced infarct size after ischemia." (PMID 24148690, 2013). "In the human heart, CYP2J2 is responsible for the epoxidation of endogenous arachidonic acid to four regioisomeric epoxyeicosatrienoic acids (EETs) released in response to certain stimuli such as ischemia." (PMID 38966316, 2024). "Moreover, cardiomyocyte-specific CYP2J2 overexpression attenuates cardiac ischemia-reperfusion injury by activating mitochondrial ATP-sensitive K+ channels and the p42/p44 MAPK pathway." (PMID 38921429, 2024). "Interestingly, CYP2J2-specific overexpression in endothelial cells showed protective effects from apoptosis of cardiomyocytes after ischemia, which finally ameliorated cardiac function." (PMID 33716791, 2021). "Conversely, the overexpression of endothelial CYP2J2 preserves the distribution of endothelial tight junctions and adherens junctions in an ANXA1-dependent manner, thus safeguarding the integrity of the BRB and shielding retinal ganglion cells from loss following ischemia-reperfusion injury." (PMID 40276708, 2025). "Overexpression of CYP2J2 increased the expression of VEGF and promoted angiogenesis in the heart after ischemia." (PMID 33716791, 2021).
heart failure (8 papers, 2010 to 2022). Inability of the heart to pump blood at an adequate rate to meet tissue metabolic requirements. "By leveraging causal network and upstream regulator analysis, we identified several candidate drivers of the observed transcriptional response to CYP2J2 silencing; these master regulators have been implicated in aberrant cardiac remodeling, heart failure, and myocyte injury and repair." (PMID 32210298, 2020). "It should be noted that we only detected the effect of CYP2J2/EET on AF associated with heart failure induced by chronic overpressure via modulating atrial fibrosis and inflammation in the present study, and further studies are needed to verify our results in other animal models or AF patients." (PMID 31749335, 2020). "Over-expression of CYP2J2 in endothelium was found to improve cardiac function by increasing angiogenesis in MI-induced heart failure, whereas over-expression of CYP2J2 by tail vein injection of rAAV9-CYP2J2 was found to attenuate ethanol-induced myocardial dysfunction." (PMID 35433888, 2022). "Recently, it was found a protective role of CYP2J2-derived EETs in heart failure." (PMID 25426071, 2014). "Thus CYP2J2-derived EETs may be a target for the development of drugs to prevent cardiac hypertrophy and cardiomyocyte apoptosis in heart failure." (PMID 25426071, 2014). "The study provides a therapeutic rationale for the potential of increasing CYP2J2 expression or EET levels to increase the levels of AMPKα2 and its beneficial effects against heart failure." (PMID 27416746, 2016).
Insulin resistance (8 papers, 2011 to 2023). Increased resistance towards insulin, that is, diminished effectiveness of insulin in reducing blood glucose levels. "We demonstrated that endothelium‐specific CYP2J2 overexpression prevented the development of aging‐related insulin resistance by improving energy homeostasis, which was associated with decreased inflammatory response." (PMID 29318723, 2018). "As adipose tissue accretion and inflammation may be causatively linked to insulin resistance, the potential effects of endothelium‐specific CYP2J2 overexpression on obesity‐induced inflammation associated with aging were explored in this study." (PMID 29318723, 2018). "Molecular genetic study demonstrated that CYP2J2 G-50T polymorphism may contribute to the pathogenesis of type 2 diabetes, partially by effects on insulin resistance, in patients with younger onset type 2 diabetes." (PMID 22189162, 2011). "CYP2J2 overexpression-derived EETs or treatment with exogenous EETs also improved insulin resistance, increased glucose uptake and restored glucose homeostasis by activation of PPARγ." (PMID 35744996, 2022). "Cardiac-specific overexpression of CYP2J2 significantly attenuated cardiac insulin resistance and glucose, and subsequently alleviated diabetic cardiomyopathy." (PMID 35744996, 2022). "In keeping with this, human obesity is characterized by a decreased expression of CYP2J2 in subcutaneous AT and a down-regulation of CYP epoxygenases associate with hepatic insulin resistance in mice." (PMID 29656108, 2018). "Taken together, these results suggested that the endothelium‐specific CYP2J2 overexpression led to stimulation of mitochondrial energy metabolism, which protected the mice against age‐related obesity and insulin resistance." (PMID 29318723, 2018). "In this study, we investigated the effects of endothelium‐specific CYP2J2 overexpression on age‐related insulin resistance and metabolic dysfunction." (PMID 29318723, 2018). "Another study shows CYP2J2 overexpression attenuates the diabetic phenotype and insulin resistance by reducing hepatic inflammation via the PPARγ." (PMID 29318723, 2018). "With the content of better understanding the mechanism of CYP2J2-EETs-sEH metabolic pathway on obesity-induced insulin resistance will provide a therapeutic strategy in combating obesity related metabolic diseases." (PMID 28440284, 2017). "Here we investigated the effects of CYP2J2-EETs-sEH metabolic pathway on insulin resistance in mice and the potential mechanisms." (PMID 28440284, 2017). "CYP2J2 was shown to attenuate age-related insulin resistance and metabolic dysfunction." (PMID 37524872, 2023). "The CYP2J2-EETs-sEH metabolic pathway has been shown in mice to have a beneficial effect on adiposity, non-alcoholic fatty liver disease, systemic inflammation, and insulin resistance." (PMID 31269743, 2019). "Collectively, our findings indicated that endothelium‐specific CYP2J2 overexpression alleviated age‐related insulin resistance and metabolic dysfunction, which highlighted CYP epoxygenase‐EET system as a potential target for combating aging‐related metabolic disorders." (PMID 29318723, 2018). "Considering Tie2‐CYP2J2‐Tr‐HF mice had a reduction in body weight gain and insulin levels, the potential effects of endothelium‐specific CYP2J2 overexpression on aging‐related adiposity and insulin resistance were explored in this study." (PMID 29318723, 2018). "As expected, endothelial CYP2J2 gene targeting significantly increased blood flow in the muscles of 16‐month‐old mice, which suggests involvement in the prevention of age‐induced insulin resistance." (PMID 29318723, 2018). "However, little is known about how CYP2J2-EETs-sEH system orchestrates the adipose tissue function and metabolism, and the mechanisms by which EETs attenuate insulin resistance need to be further explored." (PMID 28440284, 2017).
diabetes (7 papers, 2018 to 2024). "Our study investigated the expression of IL-1β, IL-10, CYP2C8, CYP2C9, CYP2J2 and sEH in HBCs from patients with type 1 diabetes mellitus (T1DM) and gestational diabetes mellitus (GDM) compared to healthy controls using immunohistochemistry." (PMID 38590527, 2024). "The median CYP2J2 staining intensity was highest in controls (median 1.5) and showed comparable levels in both types of diabetes." (PMID 38590527, 2024). "The effects of CYP2J2 overexpression on diabetes and cardiovascular disease (CVD) progression and recovery." (PMID 29966295, 2018). "The implication of CYP2J2 expression, polymorphisms, activity and, as a result, EET levels in the pathophysiology of diabetes and CVD will also be discussed." (PMID 29966295, 2018). "Together, these studies demonstrate a clear role for CYP2J2-mediated production of EETs in the prevention of diabetes and its cardiovascular consequences." (PMID 29966295, 2018). "Animal studies have consistently, and overwhelmingly, shown a protective role for EETs, and thus CYP2J2, in the etiology and progression of diabetes." (PMID 29966295, 2018). "Because EETs seem to play a role in the pathophysiology of diabetes, the aim of this study was to describe the expression profiles of EET-generating (CYP2C8, CYP2C9, CYP2J2) and EET-degrading (sEH) enzymes in HBCs from patients with T1DM and GDM compared to healthy controls." (PMID 38590527, 2024). "In our study, levels of CYP2J2 activity in subjects affected with diabetes were similar to patients without metabolic syndromes." (PMID 31269743, 2019). "There is mounting data supporting the protective role CYP2J2 plays in CVD and diabetes." (PMID 29966295, 2018).
myocardial infarction (7 papers, 2008 to 2024). Gross necrosis of the myocardium, as a result of interruption of the blood supply to the area, as in coronary thrombosis. "The CYP2J2*7 polymorphism, which is associated with reduced CYP2J2 expression and activity, is linked to a higher risk of adverse cardiovascular events including myocardial infarction." (PMID 28328948, 2017). "We studied the influence of the CYP2J2 G-50T polymorphism on the history of myocardial infarction in two study groups." (PMID 19105833, 2008). "The CYP2J2*7 polymorphism, which is associated with reduced CYP2J2 expression and activity, was linked to higher risk of adverse cardiovascular events including myocardial infarction." (PMID 28328948, 2017). "This may be another reason for the different results on the genetic impact of the CYP2J2 G-50T polymorphism on myocardial infarction." (PMID 19105833, 2008). "The present study investigates, whether the CYP2J2 G-50T polymorphism promotes the development of myocardial infarctions in patients with high cardiovascular risk profile." (PMID 19105833, 2008). "The CYP2J2 G-50T polymorphism via lower EET serum levels may negatively influence many pathways which are suspected to cause myocardial infarction." (PMID 19105833, 2008). "Although the results of the multivariate analysis are not significant, this trend, in our view, may indicate a role of the CYP2J2 G-50T polymorphism with its anti-inflammatory, vasodilatative and antithrombotic relevance in the genesis of myocardial infarctions." (PMID 19105833, 2008). "CYP2J2 overexpression in the endothelium protects against myocardial infarction-induced cardiac remodeling by promoting angiogenesis." (PMID 38921429, 2024). "Furthermore, it was confirmed that the typical defective allele CYP2J2*7 was an independent risk factor for premature myocardial infarction in the Chinese Han population and increased the risk of MI in a predominantly Caucasian population and South Indian population." (PMID 37288113, 2023). "Correlations with myocardial infarction does little to reveal which processes might be affected in CYP2J2*7 patients; EETs may alter development of atherosclerosis, vasodilation, or protection of myocardium during infarction." (PMID 28328948, 2017). "It is suggested that the CYP2J2 dependent anti inflammatory, anti thrombotic and vasodilatative mechanisms may also play a role in the development of myocardial infarctions." (PMID 19105833, 2008).
Obesity (6 papers, 2017 to 2024). Accumulation of substantial excess body fat. "The effects of endothelium‐specific CYP2J2 overexpression on aging‐associated obesity, inflammation, and peripheral insulin resistance were evaluated by assessing metabolic parameters in young (3 months old) and aged (16 months old) adult male Tie2‐CYP2J2‐Tr mice." (PMID 29318723, 2018). "In accord with its anti‐obesity effect in older mice, an aging‐related increase in mRNA level of FAS in 16‐month‐old WT mice was observed, which was inhibited by endothelium‐specific CYP2J2 overexpression." (PMID 29318723, 2018).
lung carcinoma (5 papers, 2012 to 2024). "More recently, let-7b was shown to repress the expression of epoxygenase CYP2J2 directly, and let-7b downregulation is associated with increased CYP2J2 expression in lung cancer." (PMID 27834829, 2016). "CYP2J2 has been found to play a pro-carcinogenic role in CRC, lung cancer, and bladder cancers." (PMID 39695149, 2024). "Taken together, there is strong evidence that CYP2J2 alters the progression of lung cancer through EET formation and targeting CYP2J2 activity may be a useful therapeutic strategy." (PMID 32581794, 2020).
atherosclerosis (4 papers, 2017 to 2024). A disease characterized by the build-up of fatty material and calcium deposition in the arterial wall resulting in partial or complete occlusion of the arterial lumen. "CYP2J2 overexpression by adeno-associated virus injection increased the number of EETs and protected against HFD-induced atherosclerosis in ApoE-knockout mice." (PMID 38921429, 2024). "In atherosclerosis-prone apolipoprotein E-deficient mice, recombinant adeno-associated virus-mediated CYP2J2 gene overexpression, which is associated with increased EET levels, prevented the development of high-fat diet induced atherosclerosis." (PMID 29966295, 2018).
ovarian carcinoma (4 papers, 2020 to 2024). A malignant neoplasm originating from the surface ovarian epithelium. "Compared to normal tissues, elevated expression levels of CYP2J2 were observed in bladder, kidney, lung, lymphoma, and ovarian cancer types, while suppressed expression levels of CYP2J2 were observed in cervical, colorectal, esophageal, head and neck, and liver cancer types." (PMID 34258261, 2021). "In contrast, high mRNA expression of CYP2A6, CYP2C9, CYP2J2, CYP3A4, CYP3A5, CYP3A7, and CYP3A43 connoted a good prognosis for ovarian cancer patients." (PMID 38001897, 2023). "Evidence of CYP2J2 protein expression is only available from one study reporting non-significant protein expression in ovarian cancers compared to normal ovaries." (PMID 38001897, 2023).
Stroke (4 papers, 2020 to 2025). Sudden impairment of blood flow to a part of the brain due to occlusion or rupture of an artery to the brain. "In addition, CYP2J2*7 allele has been reported to be associated with stroke and CVD (Wang SY." (PMID 35928264, 2022).